NOD2 (nucleotide binding oligomerization domain containing 2)
Diseases named in the same sentence as NOD2 in open-access papers (continued):
Sharing a sentence is not in itself a finding about the gene and the disease.
Crohn disease (continued). "These “bystander” effects reflect their shared regulatory architecture with known causal genes, and our observations around met-QTLs mirror recent findings at the SORT1 and NOD2 loci (associated with LDL cholesterol and Crohn’s disease, respectively)." (PMID 31978332, 2020). "Of note, the authors found a lower expression of Pellino3 protein in the colons of patients with Crohn’s disease, supporting the theory that Pellino3 is an important mediator of NOD2 signaling in the gut." (PMID 31632962, 2019). "Although many studies have identified the potential role of NOD2 in Crohn’s disease, multiple other factors can also contribute to increased risks and act as different pathways for Crohn’s disease." (PMID 31723489, 2019). "Approximately 20% of the genetic susceptibility of Crohn's disease is related to three main mutations (SNP8, SNP12 missense mutations, and SNP13 frameshift mutation) of the NOD2 gene." (PMID 31723489, 2019). "Strong evidence suggests a relationship between Crohn’s disease and the NOD2 gene (or CARD15), which is situated on chromosome 16." (PMID 31723489, 2019). "NOD2 has been involved in the development of Crohn's disease, early onset sarcoidosis, Blau syndrome, autoimmune disease, allergy, and asthma (Ni, Chen, Wu, Zhu, & Song, 2017)." (PMID 30950247, 2019). "The results were in line with another study showing a strong relationship between NOD2 and Crohn’s disease." (PMID 31723489, 2019). "The analysed variants of the CARD15/NOD2 and DLG5 genes can significantly contribute to the development of IBD, i.e., Crohn's disease and ulcerative colitis." (PMID 30648106, 2018). "Gene‐gene interaction analysis revealed significant interactions between MST1 and other susceptibility genes, including NOD2, MUC19 and ATG16L1 in contributing to Crohn's disease risk." (PMID 29441677, 2018). "NOD2 mutations have been evidenced in granulomatous diseases, including Blau syndrome (BS), early onset sarcoidosis (EOS) and Crohn’s disease (CD)." (PMID 29554915, 2018). "In Crohn’s disease, many associations with autophagy-related genes, such as ATG16L1, IRGM, NOD2, and others, have been reported." (PMID 30583538, 2018). "Collectively, we provide the rational for targeting therapeutically NOD2 signaling in familial cold auto-inflammatory syndrome by unveiling an unappreciated molecular link with the pathogenesis of Crohn’s disease." (PMID 30559449, 2018). "NOD2/CARD15, TLR4 and CD14 mutations in Scottish and Irish Crohn's disease patients: evidence for genetic heterogeneity within Europe?" (PMID 28819537, 2017). "Clinical form of resultant autoinflammatory condition depends on NOD2 genotype; usually patients with NOD2 defects present with Blau syndrome, NOD2-associated autoinflammatory disease (NAID) or Crohn’s disease." (PMID 28750667, 2017). "We recently reported that the nucleotide binding oligomerization domain 2 (NOD2), a cytoplasmic PRR and a known susceptibility marker for Crohn’s disease, was upregulated by HCMV resulting in induction of IFN-β and inhibition of HCMV11." (PMID 26830977, 2016). "Overall, our findings provide evidence that Crohn’s disease patients with severe clinical phenotypes have an impairment of MBL-MASP functional activity and that this defect is associated with MBL2 and NOD2 variants." (PMID 27404661, 2016). "This study will enable us to determine the relationship between MBL2 and NOD2 in Crohn’s disease and the way in which each affect the other by studying the signalling pathways." (PMID 27404661, 2016). "In contrast, mutations in the second major Crohn's disease susceptibility factor, ATG16L1, disrupt an inhibitory interaction with NOD2 and consequently increase the activation of RIPK2." (PMID 26320862, 2015). "The interactions between TLR9 polymorphisms and allelic variants in NOD2 and IL23R differentially modulate susceptibility to Crohn's disease." (PMID 26090491, 2015).
Crohn disease (continued). "Nucleotide oligomerization domain 2 (NOD2) is a cytoplasmic pattern recognition receptor that has been connected with a variety of inflammatory disorders including Crohn’s disease, Blau syndrome, asthma, sarcoidosis, and arthritis." (PMID 26500656, 2015). "Genes that were significant with at least two variables include: BTNL2 for alopecia areata, NOD2 for Crohn’s disease, PLA2R1 for membranous neuropathy, LMO1 for neuroblastoma, and TNPO3, UBE2L3, HLA-DRA, and HIC2 for systemic lupus erythematosus." (PMID 26170196, 2015). "This highlights the complex contributions of NOD2 polymorphisms to Crohn’s disease and reiterates the importance of both RIPK2 binding and membrane association in NOD2 signaling." (PMID 26500656, 2015). "Conversely, NOD2-defective dendritic cells from Crohn’s disease patients had marked impairment in inducing Th17 polarization from memory T-cells." (PMID 25136265, 2014). "Mutation of NOD2 or RIP2 (downstream of NOD2) disrupts the balance between commensal microbes and is associated with Crohn’s disease, an inflammatory intestinal disorder increasing the risk of colitis-associated colorectal carcinoma." (PMID 28548063, 2014). "A link between NOD2 and ATG16L1 as presented in this model is of great fundamental importance, because SNPs in both proteins are implicated in Crohn's disease and hamper autophagy induction." (PMID 25520185, 2014). "Spurred on by the discovery of NOD2, additional linkage studies of Crohn's disease (and other common complex diseases) were undertaken; The results of these studies were largely disappointing, with few loci being consistently replicated." (PMID 24913378, 2014). "Blau syndrome and Crohn’s disease are associated with the CARD-containing NLR, NOD2/NLRC2 with NACHT domain mutations occurring in Blau syndrome, while LRR domain mutations of NOD2 are reported for Crohn’s disease." (PMID 24062743, 2013). "The study of NOD2 linkage to Crohn’s disease has been extended to encompass a key role of NOD1 and 2 in the regulation of autophagy." (PMID 24137163, 2013). "A recent genome-wide association study detected and replicated susceptibility factors in CCDC12, C13orf31, NOD2, TNFSF15, RIP2K, and the HLA-DR/DQ locus and revealed a striking overlap with Crohn's disease susceptibility factors." (PMID 23350010, 2013). "We also show that VAAST 2.0 outperforms KBAC, WSS, SKAT, and variable threshold (VT) using published case-control datasets for Crohn disease (NOD2), hypertriglyceridemia (LPL), and breast cancer (CHEK2)." (PMID 23836555, 2013). "For Crohn's disease, there are two SNPs (rs2066844, MAF = 5.29%; rs2066845, MAF = 1.10%) in the NOD2 gene that are known to be causal." (PMID 23762022, 2013). "Polymorphisms in the CARD15/NOD2 gene, in addition to functional variants of the toll-like receptor-4 (TLR4) and CD14 genes, have been associated with the development of Crohn’s disease." (PMID 22605977, 2012). "Considering the role of SHIP-1 in NOD2 signaling, it has been recently demonstrated that SHIP-1-deficient mice develop a Crohn’s disease (CD) like ileitis." (PMID 22815893, 2012). "Since associations between CNO and Crohn's disease, a multifactorial autoinflammatory disease, have been reported, Morbach and colleagues analyzed CNO patients for NOD2/CARD15 mutations." (PMID 22685464, 2012). "The best studied genetic example, NOD2 in Crohn's disease, is highlighted as a model which encompasses these interactions and has been shown to depend on butyrate for normal function." (PMID 22518336, 2012). "In Crohn's disease, NOD2 SNPs 8, 12, and 13 have been correlated with distinct disease phenotypes, in particular with the site of Crohn's disease within the gastrointestinal tract and with the age of onset." (PMID 23119165, 2012).
Crohn disease (continued). "One possible explanation for the involvement of defective autophagy in Crohn's disease inflammation couples the risk alleles in ATG16L1 and NOD2 (nucleotide-binding oligomerization domain containing 2) to an impaired clearance of microorganisms." (PMID 21490934, 2011). "In gain of function mutations in the Nod2 gene, there is an induction of TH1 and IL-17 secreting T helper response that promotes tissue damage and Crohn's disease." (PMID 21272292, 2011). "Indeed, the clear association of Nod2 polymorphisms with defective bacterial killing suggests this function could significantly underlie the contribution of commensal flora to the pathogenesis of Crohn's disease." (PMID 20531959, 2010). "Genetic variation in the extracellular (TLR4) and intracellular (NOD2) endotoxin sensing system have been related to sepsis, Crohn's disease, premature delivery and atherogenesis." (PMID 18382655, 2008). "In some Crohn's disease (CD) patients, for example, mutations in a microbial product sensor NLR, the NOD2/CARD15 protein, is associated with the disease susceptibility." (PMID 18779861, 2008). "It is known that NODsignaling involves the activation of NFκB pathway, but surprisingly,mutations in the CARD15 gene, affecting NOD-2 function, increase the susceptibility to Crohn’s disease." (PMID 18350123, 2008). "Genetic evidence supports a role of PRR in IBD, since polymorphisms in NOD2 and to a lower extent in TLR9 genes have been linked with Crohn's disease." (PMID 17375199, 2007). "Variants in CARD15, the gene encoding the NOD2 protein, are associated with Crohn disease (CD), a chronic inflammatory disorder of the human intestine, asthma and atopic eczema." (PMID 17980027, 2007). "Genetic variation in the CARD15 gene, which encodes NOD2, was previously shown to result in a barrier defect that causes chronic inflammatory disorders (e.g. Crohn disease)." (PMID 17980027, 2007). "Nucleotide-binding oligomerization domain 2 (NOD2), initially described as a susceptibility gene for Crohn's disease, is an intracellular protein containing leucine-rich repeats (LRRs) similar to those found in TLRs." (PMID 16322770, 2005). "Our findings identify a NOD2-estrogen regulatory axis that supports intestinal homeostasis and suggest that hormonal signaling may contribute to sex-specific aspects of Crohn's disease." (PMID 42263101, 2026). "Furthermore, absolute CCL20 levels were comparable between NOD2-mutant and wildtype patients with Crohn’s disease." (PMID 40542081, 2025). "Recent evidence suggests that inhibiting the ABHD17A, B, and C isoforms can rescue the S-acylation and signaling ability of some, but not all, Crohn’s disease-associated NOD2 variants." (PMID 40613780, 2025). "Furthermore, Nod2 (CARD15) is a protein exclusive to macrophages, and recent studies have linked NOD2 gene alterations to Crohn’s disease." (PMID 39148739, 2024). "These patients appeared phenotypically distinct from pediatric Blau syndrome and Crohn’s disease and lacked granulomatous inflammation seen in these other NOD2-associated conditions." (PMID 39430755, 2024). "Polymorphisms in nucleotide-binding oligomerization domain 2 (NOD2) contribute the largest fraction of genetic risk for Western Crohn’s disease so far, while we found no mutation in the Chinese Han population." (PMID 39001900, 2024). "In pure cells with NOD2 shifter mutations associated with Crohn's disease, mutant NOD2 fails to recruit ATG16L1 to the plasma membrane, and autophagosome encapsulation of invading bacteria is impaired." (PMID 39883213, 2024). "Several studies have identified a significant role for NOD2 in IBD especially Crohn’s Disease (CD)." (PMID 36694274, 2023). "Control of Map in monocytes from Crohn’s disease patients heterozygous for the common NOD2 mutations was not significantly hampered compared to patients homozygous for functional NOD2, suggesting NOD2 haplosufficiency or no role for NOD2 in Map control." (PMID 37262021, 2023).
Crohn disease (continued). "While an increase of immature macrophages has been correlated with the endoscopic severity score of the disease, a defect of mo-DCs function, including a decrease in TH17 activation and IL-12 production in response to NOD2 stimulation has been observed in Crohn’s disease (CD) patients." (PMID 37415975, 2023). "NOD2 is a CARD-containing protein encoded by the NOD2/CARD15 gene, one of the most investigated IBD genes, since its mutations have been linked to an increased risk of developing Crohn’s disease." (PMID 37998389, 2023). "Despite knowledge of the associated between NOD2/CARD15 mutations and Crohn’s (especially ileal Crohn’s), the true extent of the importance of the NOD2/CARD15 gene in Crohn’s disease remains incompletely understood and has yet to permeate into clinical practice." (PMID 37762727, 2023). "These pathways suggest a hyper-activated status in NOD2hi patients, in line with the higher activation and immune response found in Crohn’s disease patients without NOD2 mutations, exhibiting increased cytokine receptors and decreased microRNA expression." (PMID 37876927, 2023). "Blau syndrome is associated with apparent NOD2 gain-of-function mutations rather than a loss-of-function typically observed for Crohn’s disease." (PMID 37869013, 2023). "The NOD2 gene encodes a cytosolic PRR recognizing MDP—a peptidoglycan motif common to all bacteria, considered the strongest susceptibility gene associated with Crohn’s disease." (PMID 36430390, 2022). "NOD2 plays a role in the immune response to intracellular bacterial lipopolysaccharides by triggering activation of MAP kinases and NFκB signaling and mutations in NOD2 have been correlated with increased risk of Crohn’s disease." (PMID 35446871, 2022). "Accordingly, TRIM27 might affect NOD2-mediated proinflammatory responses to promote the progression of Crohn’s disease." (PMID 36200036, 2022). "Three major NOD2 variants, R702W, G908R, and L1007fsinsC, and some minor variants in the C-terminal LRR region and the helix domain 2 (HD2) have been found to be associated with the development of Crohn’s disease in both European and American populations." (PMID 36146565, 2022). "A substantial number of people suffering from Crohn's disease carry loss of function mutations in the NOD2/CARD15 gene, and in dairy cattle, polymorphisms of NOD2/CARD15 are associated with Johne's disease and NOD-2/CARD15 deficient mice have impaired resistance to mycobacterial infections." (PMID 36733765, 2022). "Another likely pathogenic variant rs2076754 (c.C1295T: p.A432V) in the NOD2 gene associated with Blau syndrome/ Crohn’s disease does not have any significant difference in comparison with the wild type." (PMID 34905135, 2021). "One example of this mechanism is the NOD2 gene, mutations that generate a non-functional version of NOD2 are a risk factor for Crohn’s disease, and NOD2 risk variants are associated with activated immune cells and fibrosis." (PMID 35127705, 2021). "This provides a strong molecular basis for the contribution of vitamin D deficiency to the pathogenesis of Crohn's disease (CD) because the interaction of ATG16L1 and NOD2 participate in an autophagy‐dependent antibacterial pathway implicated in CD pathogenesis." (PMID 33559391, 2021). "Interestingly, mutations in CARD15/NOD2 are also associated with other diseases with inflammatory involvement, such as Crohn ́s disease and arthritis." (PMID 34294115, 2021). "Moreover, they took into account two additional SNPs (SNP8—R702W and SNP12—G908R) present in the NOD2/CARD15 gene, which are associated with increased susceptibility to Crohn's disease." (PMID 32596371, 2020). "Finally, it has been repeatedly demonstrated that the NOD2 genotype impacts on the ileal microbiome in Crohn's disease." (PMID 32351509, 2020).
Crohn disease (continued). "NOD2 is considered as one of the genetic risk factors in the pathogenesis of IBD, and it is also recognized as the strongest single genetic susceptibility locus in Crohn’s disease." (PMID 32932716, 2020). "On the contrary, NOD2 can also regulate the expression of miR-21 in dendritic cells for the secretion of IL-23, the immunomodulatory mechanism of which is involved in the pathogenesis of Crohn’s disease." (PMID 32932716, 2020). "This article will discuss a number of studies to identify whether there is a relationship between Crohn’s disease and the NOD2 gene." (PMID 31723489, 2019). "NOD2 and ATG16L1 genetic variants that lead to reduced function are associated with Crohn disease." (PMID 31610723, 2019). "Remarkably, miR-122 targets NOD2 to decrease intestinal epithelial cell injury in Crohn’s disease." (PMID 30736753, 2019). "Human genome wide association studies (GWAS) have shown between 30 and 50% of Crohn's disease patients have NOD2 polymorphisms, suggesting NOD2 polymorphisms are a risk factor for disease, but alone, not sufficient or necessary for disease." (PMID 32010704, 2019). "A hyper-responsive phenotype was found in Crohn’s disease patients without NOD2 mutations, characterized by upregulated cytokine receptors and general downregulation of microRNA expression." (PMID 29263823, 2017). "It is clear from our results, and in agreement with the work of other researchers investigating different NOD2 polymorphisms, that not all Crohn’s disease-associated NOD2 polymorphisms result in the same degree of functional impact." (PMID 26500656, 2015). "An excellent example of this is NOD2/CARD15, selected for study in transplant outcomes as SNPs in NOD2/CARD15 were found to be associated with Crohn’s disease, and there are similarities in this chronic inflammatory disorder of the gastrointestinal tract and GvHD symptoms." (PMID 25700678, 2015). "NOD2 exonic variations in Iranian Crohn's disease patients in 2011 were studied." (PMID 26468345, 2015). "As an illustration, while NOD2 has been strongly associated with Crohns’ disease in patients from the Western world, this has not been observed among Asian patients." (PMID 26378020, 2015). "In addition, a truncated version of NOD2 found in some patients with Crohn's disease cells leads to the retention of ATG16L1 in cytoplasm, inhibiting its recruitment to plasma membrane and reducing autophagic activity." (PMID 24818040, 2014). "Recently we have described an increased frequency of NOD2 mutations in SBS patients without underlying Crohn’s disease." (PMID 24597572, 2014). "The common NOD2 gene polymorphisms conferring susceptibility to Crohn's disease in Western populations are absent in Indian IBD patients." (PMID 25191865, 2014). "Moreover, the 3020insC NOD2 mutant protein in patients with Crohn's disease actively inhibits IL-10 production by impairing hnRNP-A1 phosphorylation and hnRNP-A1 binding to the IL-10 locus." (PMID 23675299, 2013). "This interaction will likely be important to our understanding of chronic inflammatory diseases; the interaction between NOD2 and complement signaling may be of particular interest in Crohn’s disease." (PMID 24634797, 2013). "NOD2 is an intracellular receptor for the bacterial cell wall component muramyl dipeptide (MDP), and variants of NOD2 are associated with chronic inflammatory diseases of barrier organs (e.g., Crohn's disease, asthma, and atopic eczema)." (PMID 22330585, 2012). "However, it is still poorly understood how polymorphisms in the NOD2 LRR (L100fs) or NBD (R334W, R334Q, and L469F) domains contribute to Crohn’s disease and Blau syndrome, respectively." (PMID 23162548, 2012). "Furthermore, recent genome-wide association studies in humans affected by Crohn's Disease have revealed several susceptibility genes (e.g., NOD2/CARD15), which are implicated in defective bacterial killing as a consequence of impaired innate immunity." (PMID 22720094, 2012).